JAK2 (Janus kinase 2)
Diseases named in the same sentence as JAK2 in open-access papers (continued):
Sharing a sentence is not in itself a finding about the gene and the disease.
myeloproliferative neoplasm (continued). "Polycythemia vera (PV) is one of the three classic BCR/ABL-negative myeloproliferative neoplasm (MPN) and is characterized by an increased red blood cell mass induced by driver mutations in the JAK2 gene." (PMID 34462786, 2021). "The majority of patients with the myeloproliferative neoplasm (MPN) polycythemia vera (PV), which is characterized by erythrocytosis, harbour a janus kinase 2 (JAK2) mutation." (PMID 35844679, 2021). "Myeloproliferative neoplasms (MPN) are clonal hematologic malignancies with dysregulated myeloid blood cell production driven by JAK2, calreticulin, and MPL gene mutations." (PMID 34680185, 2021). "Polycythemia vera (PV) is a BCR-ABL1-negative myeloproliferative neoplasm (MPN) characterized by excessive proliferation of erythroid, myeloid, and megakaryocytic components in the bone marrow, mainly due to a Janus kinase 2 gene mutation (JAK2V617F)." (PMID 33677466, 2021). "The myeloproliferative neoplasms (MPN) are usually sporadic diseases characterized by increased JAK/STAT pathway signaling due to a somatic driver mutation in either the JAK2, CALR, or MPL gene." (PMID 34209587, 2021). "Hematopoietic neoplasms with chromosomal translocations involving JAK2 are rare, and most of them show myeloproliferative neoplasm (MPN)‐associated features, often with eosinophilia." (PMID 31885183, 2020). "Constitutively activating JAK2 mutants drive biased myelopoiesis and promote development of myeloproliferative neoplasms (MPN) or clonal hematopoiesis, conditions associated with increased risk of ACD." (PMID 32086626, 2020). "In particular, an activating point mutation in JAK2 (JAK2V617F) was described as being highly frequent in chronic myeloproliferative neoplasms (MPN) that promote disease progression." (PMID 31861612, 2019). "Importantly, oncogenic mutation of JAK2 in myeloproliferative neoplasms was recently shown to induce surface PD-L1 expression through increased promotor activity, and this transformation of myeloid cells was associated with a reduction of T-cell metabolic activity and proliferation." (PMID 31185600, 2019). "Thereby, JAK2-V617F is a frequent driver of myeloproliferative neoplasms (MPN), a group of myeloid malignancies caused by an increased proliferation and cytokine production of different myeloid cell types." (PMID 31398915, 2019). "Nevertheless, activating JAK2-V617F mutations are the most frequent driver mutations of myeloproliferative neoplasms (MPN)." (PMID 31398915, 2019). "Splanchnic Vein Thrombosis (SVT) is strongly associated with underlying JAK2 V617F positive myeloproliferative neoplasms (MPN)." (PMID 30574023, 2018). "Essential thrombocythemia (ET) is a myeloproliferative neoplasm (MPN) derived from clonal expansion of hematopoietic progenitor cells carrying a mutation in the cytokine receptor/JAK2-signaling pathway (JAK2, CALR, or MPL)." (PMID 29515972, 2018). "The clinical significance of CN-LOH in AML is not yet known, however these lesions have been shown to represent therapeutic targets as in JAK2 myeloproliferative neoplasms and there are suggestions that they may be associated with inferior outcomes in pediatric AML." (PMID 29899868, 2018). "Identification of the JAK2 V617F mutation is a major diagnostic criterion for the classical myeloproliferative neoplasms (MPN) of polycythemia vera, essential thrombocythemia and primary myelofibrosis." (PMID 29383013, 2018). "A recent study has reported strong synthetic lethality between RECQL5 and an activating V617F mutation in the JAK2 tyrosine kinase in patients with myeloproliferative neoplasms, and it is possible that the JAK/STAT cascade may be worthy of further exploration in the context of NMC." (PMID 29348827, 2017). "Common germline single-nucleotide polymorphisms (SNPs) at JAK2 locus have been associated with Myeloproliferative neoplasms (MPN)." (PMID 26843622, 2016).
myeloproliferative neoplasm (continued). "Previous study showed its anti-neoplastic activities against cells with JAK2 V617F mutation, a hallmark for human myeloproliferative neoplasm (MPN), and on a T-cell ALL." (PMID 28050230, 2016). "Clonal proliferation in myeloproliferative neoplasms (MPN) is driven by somatic mutations in JAK2, CALR or MPL, but the contribution of inherited factors is poorly characterized." (PMID 25849990, 2015). "Hence any model for activation must remove the PK domain away from the kinase domain, and it is notable that myeloproliferative neoplasms with constitutive JAK2 activation possess point mutations in the PK domain or the linker to the adjacent SH2 domain, rather than the kinase domain." (PMID 25656053, 2015). "In 2005, V617F point mutations in JAK2 were identified in a subset of myeloproliferative neoplasm (MPN) patients." (PMID 24830942, 2014). "Ruxolitinib, a potent and selective JAK1/JAK2 inhibitor significantly inhibited interleukin-6 signaling and proliferation of cells that harbor JAK2-V617F mutation, and presently, is being investigated in clinic in patients with myeloproliferative neoplasms (MPNs)." (PMID 24930769, 2014). "Additionally, the Mayo reported the presence of a JAK2 V617F mutation, providing confirmation for the coexistence of an early myeloproliferative disorder." (PMID 25386371, 2014). "Clinical evidence for the relevance of this domain was obtained in 2005, when an acquired point mutation in the JH2 domain of JAK2 (Val 617 to Phe substitution, V617F) was identified in myeloproliferative neoplasm (MPN) patients." (PMID 21533163, 2011). "Thrombocytosis on full blood count, previously uninvestigated, prompted hematological assessment and led to the diagnosis of a JAK2-positive myeloproliferative neoplasm, for which cytoreductive therapy was initiated alongside anticoagulation." (PMID 41664792, 2026). "The presence of mutations in the JAK2, CALR, and MPL genes is essential for the diagnosis of myeloproliferative neoplasms." (PMID 39960584, 2026). "Beyond the paediatric setting, haematological cancers driven by single genetic events, such as mutant-JAK2 driven myeloproliferative neoplasms, are also characterized by slow clonal outgrowth over decades." (PMID 40205062, 2025). "Polycythemia vera (PV) is a myeloproliferative neoplasm characterized by elevated hemoglobin and hematocrit levels, most commonly driven by constitutive activation of the JAK2 signaling pathway." (PMID 40429942, 2025). "There is superior activity of HDAC inhibitors (HDACi) in patients with myeloproliferative neoplasms (MPNs) that carry the Janus kinase-2 point mutant JAK2V617F." (PMID 40877230, 2025). "JAK mutations, particularly those affecting JAK1 and JAK2, are oncogenic in both acute lymphoblastic leukemia (ALL) and myeloproliferative neoplasms (MPN)." (PMID 40470252, 2025). "In myeloproliferative neoplasms (e.g., JAK2 V617F+ essential thrombocythemia), thrombotic events often precede hematologic abnormalities by years." (PMID 40602171, 2025). "The acquired JAK2-V617F mutation plays a causal role in myeloproliferative neoplasms (MPN)." (PMID 40841769, 2025). "Histone demethylases KDM4C and KDM3C were recently identified as a signaling effector of mutated JAK2 and a target gene of the transcription factor NFE2, which is overexpressed in myeloproliferative neoplasms." (PMID 40374809, 2025). "Myeloproliferative neoplasms (MPNs) also constitute a major etiological factor in BCS, particularly in cases involving the Janus kinase 2 (JAK2) V617F somatic mutation." (PMID 40895862, 2025). "A meta-analysis identified high prevalence and strong association between the Jak2 mutation, SVT, and the subsequent diagnosis of myeloproliferative neoplasms." (PMID 41567421, 2025).
myeloproliferative neoplasm (continued). "This first-reported case of SF3B1-mutated myelodysplastic/myeloproliferative neoplasm with thrombocytosis (MDS/MPN-SF3B1-T), harboring coexisting ASXL1, JAK2 p.R683G, and CBL mutations challenges conventional genomic prognostic paradigms." (PMID 40772034, 2025). "Recently, more selective JAK2 inhibitors have been developed and used for the treatment of myeloproliferative neoplasms." (PMID 39891728, 2025). "Many studies and the revised WHO criteria have shown that the JAK2 V617F, CalR, and MPL gene mutations are crucial for the diagnosis of chronic myeloproliferative neoplasms." (PMID 40572650, 2025). "The clonal composition of myeloproliferative neoplasms (MPN) harboring both JAK2 V617 F and BCR::ABL1 and the outcomes of these patients are unclear and management remains challenging." (PMID 40299271, 2025). "Therefore, we develop two JAK2-V617F-driven myeloproliferative neoplasm (MPN) mouse models harboring ruxolitinib resistance mutations." (PMID 40413183, 2025). "A proportion of patients with JAK2 mutations develop myeloproliferative neoplasms (MPN), characterized by the proliferation of stem cells such as mature granulocytes (primary myelofibrosis), red blood cells (polycythemia vera), and/or platelets (essential thrombocythemia)." (PMID 40792243, 2025). "The histone demethylases KDM4C (JMJD2C) and KDM3C (JMJD1C) were recently identified as signaling effectors of mutated JAK2 and target genes of the transcription factor NFE2, which is overexpressed in myeloproliferative neoplasms." (PMID 40140631, 2025). "The JAK2 46/1 haplotype, also known as the GGCC haplotype, is an inherited genetic variation within the Jak2 gene locus that has become a focal point in research related to oncogenesis, particularly in Myeloproliferative Neoplasms (MPNs)." (PMID 41226376, 2025). "Other risk factors, including obesity, smoking, immobility, myeloproliferative neoplasms, JAK2 (Janus Kinase 2) mutation, multiple pregnancies, and advanced maternal age, increase the thrombogenic risk by 1.5–2 times." (PMID 39941603, 2025). "Particularly striking was the substantially lower frequency of JAK2-CH in MCPS than in UKB, and it is tenable that this underlies the lower prevalence of myeloproliferative neoplasms, most of which are JAK2-driven, in Hispanic populations." (PMID 39948438, 2025). "HDAC inhibitors have also been shown to enhance the efficacy of JAK2 inhibitors in myeloproliferative disorders by downregulating JAK2 and JAK2 V617F through acetylation of the chaperone protein HSP90." (PMID 41144126, 2025). "JAK2 inhibitors, such as ruxolitinib and fedratinib, have been approved for use in adults with myeloproliferative disorders, and their potential in pediatric leukemia is actively being explored." (PMID 40486651, 2025). "The JAK2 V617F mutant was recognized in a patient suffering from myeloproliferative disorder (MPD) and hypertrophic HCM, indicating that HCM is associated with JAK2." (PMID 40271123, 2025). "Patients with myeloproliferative diseases and BCS are typically younger, female, with inherited thrombophilia, and with the JAK2 V617F mutation." (PMID 40242703, 2025). "Another JAK2 inhibitor currently under investigation is fedratinib, which is more selective for JAK2 and has shown efficacy in treating myeloproliferative disorders in adults." (PMID 40486651, 2025). "We also wanted to establish the association between the studied polymorphisms of the XPC, XPD, XPF, and XPG genes and the JAK2, CALR driver mutations and to identify possible predictors in the appearance of myeloproliferative neoplasms." (PMID 38541232, 2024). "As this patient progressed from a JAK2-mutant myeloproliferative neoplasm (MPN) or chronic myelomonocytic leukemia (CMML) to AML, this cell hints at the presence of residual MPN- or CMML-related blood cells at the time of CK-AML diagnosis." (PMID 39587361, 2024).
myeloproliferative neoplasm (continued). "In this review, we summarize molecular drug resistance biomarkers in targeted therapies in BCR::ABL1-driven chronic myeloid leukemia (CML) and JAK2-driven myeloproliferative neoplasms (MPNs)." (PMID 39104388, 2024). "In some patients with myeloproliferative neoplasms (MPN), two genetic mutations are often found: JAK2 V617F and one in the TET2 gene." (PMID 38363386, 2024). "A single somatic mutation, V617F (exon 14) in the JH2 domain of JAK2, which disrupts the JH1-JH2 autoinhibitory interaction, leading to JAK2 hyperactivation, is a common hallmark of the BCR::ABL1-negative myeloproliferative neoplasms." (PMID 38649367, 2024). "In pre-clinical studies of myeloproliferative neoplasms, Ruxolitinib inhibited the proliferation of JAK2 V617F-driven Ba/F3 cells that constitutively phosphorylate JAK2." (PMID 38339245, 2024). "Particularly, JAK2/3 are suitable targets for the treatment of hematologic tumors and myeloproliferative neoplasms; however, the discovery of JAK2/3 inhibitors remains a challenge." (PMID 39339202, 2024). "PU-H71 can directly bind to oncogenic JAK2 mutants, such as JAK2V617F, which are common driver mutations in myeloproliferative neoplasms (MPNs)." (PMID 39564119, 2024). "JAK2 is a kinase with crucial roles in the growth and development of hematological malignancies, particularly myeloproliferative neoplasms." (PMID 39704857, 2024). "Here, we investigated EPO and thrombopoietin (TPO) induced SOCE and PLCγ1 activation in hematopoietic cells exhibiting activating mutations in JAK2 and CALR which are disease-initiating events in myeloproliferative neoplasms (MPNs)." (PMID 38509561, 2024). "The differential diagnosis for IHES includes primary HES associated with myeloproliferative neoplasms, such as those with genetic mutations in PDGFRA, PDGFRB, FGFR1, and JAK2." (PMID 39867100, 2024). "Both the SHP2 inhibitor RMC4550 and the JAK2 inhibitor decreased RAS-GTP levels in myeloproliferative neoplasm cells, and their combined employment enhanced ERK inactivation and increased apoptosis." (PMID 39014007, 2024). "AT9283, originally identified as a multi-target kinase inhibitor against aurora A, Aurora B, JAK3, JAK2, and Abl, has been reported to be effective drug against leukemia cells, myeloproliferative diseases and various solid cancer cell lines." (PMID 38414025, 2024). "Both UKBB and FinnGen show a strong correlation of JAK2 V617F with myeloproliferative disease and polycythemia vera." (PMID 39062663, 2024). "Ruxolitinib is a novel potent biologic agent that inhibits Janus kinase 1 (JAK1) and Janus kinase 2 (JAK2), reserved for patients with myeloproliferative diseases." (PMID 38576050, 2024). "A JAK2 inhibitor (ruxolitinib) was initially used in the treatment of JAK2/V617F-positive myeloproliferative disorders." (PMID 39659792, 2024). "The patient was eventually diagnosed with a JAK2-positive myeloproliferative neoplasm with essential thrombocythemia and he was treated with hydroxycarbamide with a plan to give radioactive phosphorus as per haematology review." (PMID 39371771, 2024). "Somatic variants were rarely identified with VAFs >=10% in nail samples and were primarily confined to disease-defining alterations associated with loss of heterozygosity (LOH) in the tumor sample, such as JAK2 and TET2 in myeloproliferative neoplasms." (PMID 37898613, 2023). "JAK2 gain-of-function mutations, leading to constitutive phosphorylation of STAT3, STAT5, and JAK2 itself, have been recognized in a high proportion of myeloproliferative neoplasms." (PMID 37834225, 2023). "In myeloproliferative neoplasms (MPNs), a recent study showed that constitutive JAK2 activation induces chromatin-level alterations, particularly in enhancer utilization which promotes NFkB signaling, resulting in resistance to JAK inhibition." (PMID 36740715, 2023).
myeloproliferative neoplasm (continued). "Polycythemia vera (PV) is the most prominent myeloproliferative neoplasm (MPN), the final phenotypic effect of Janus kinase-2 (JAK2) somatic gene mutations, and the most frequently MPN accompanied by arterial and venous thrombosis." (PMID 37228964, 2023). "Aberrant JAK2 signaling and myeloproliferative neoplasms are closely related; however, the data suggest that tumor cells are insensitive to anti‐JAK2 treatment regimens; therefore, effective treatments are needed." (PMID 37162273, 2023). "Primary myelofibrosis (PMF) is a rare myeloproliferative neoplasms (MPN) characterized by mutations in three driver genes that cause an hematopoietic stem cell – derived monoclonal proliferation: janus kinase 2 (JAK2), calreticulin (CALR) or MPL proto-oncogene (MPL)." (PMID 37822925, 2023). "Primary myelofibrosis (PMF), polycythemia vera (PV) and essential thrombocythemia (ET) form the classical BCR-ABL1-negative myeloproliferative neoplasms (MPNs) that are driven by a constitutive activation of JAK2 signaling." (PMID 37771602, 2023). "Myeloproliferative neoplasms (MPN) are characterized by uncontrolled expansion of myeloid cells, disease‐related mutations in certain driver‐genes including JAK2, CALR, and MPL, and a substantial risk to progress to secondary acute myeloid leukemia (sAML)." (PMID 36814396, 2023). "This sensitized for treatment with the JAK1/JAK2 inhibitor ruxolitinib, which is approved for the treatment of myeloproliferative neoplasms and was shown to penetrate the blood–brain barrier in mice." (PMID 37495858, 2023). "In a meta-analysis of 150 cases to compare gene mutational profiles across MDS, MDS/MPN, and MPN, the results confirmed the low frequency of JAK2 mutations in MDS and its more frequent occurrence among myeloproliferative neoplasms and cases with overlap features, particularly MDS/MPN-RS-T." (PMID 36810551, 2023). "Other cancer genes with high mutation frequencies include KRAS (mutated in 84%) of pancreatic adenocarcinomas and PTEN (67%) of uterine corpus endometrial carcinomas, and JAK2 (75%) of myeloproliferative neoplasms." (PMID 37550388, 2023). "Calreticulin (CALR) mutations present the main oncogenic drivers in JAK2 wildtype (WT) myeloproliferative neoplasms (MPN), including essential thrombocythemia and myelofibrosis, where mutant (MUT) CALR is increasingly recognized as a suitable mutation-specific drug target." (PMID 36813992, 2023). "Although JAK2 inhibitors have only been approved for the treatment of myeloproliferative disorders, several preclinical studies have shown the implication of the JAK/STAT pathway in solid tumours." (PMID 37210549, 2023). "In 2013, CALR mutations were first identified as driver mutations in myeloproliferative neoplasm (MPN) and were found in 70–80% of patients with JAK2 V617F-negative essential thrombocythemia (ET) and primary myelofibrosis (PMF), with characteristic clinical findings." (PMID 36359414, 2022). "Various JAK2 inhibitors have been developed as treatments for leukemia, myelofibrosis, and myeloproliferative neoplasms." (PMID 35562984, 2022). "A single point mutation of the tyrosine kinase JAK2, common in myeloproliferative cancers, results in upregulation of La/SSB in both cell culture and in CD34+ progenitor cells from patients with myeloproliferative neoplasms." (PMID 34636174, 2022). "Inhibition of PI3K/AKT/mTOR enhanced the effect of JAK2 inhibitors on primary human myeloproliferative neoplasm cells." (PMID 35773269, 2022). "It’s noteworthy that we didn’t include two cases of JAK2 V617F myeloproliferative neoplasms in our analysis, preceded by IBD." (PMID 35494055, 2022). "JAK2-V617F is the most common mutation in myeloproliferative neoplasm (MPN)." (PMID 35318612, 2022).